BRAF (B-Raf proto-oncogene, serine/threonine kinase)
Diseases named in the same sentence as BRAF in open-access papers (continued):
Sharing a sentence is not in itself a finding about the gene and the disease.
melanoma (continued). "The combat of melanoma by using the targeted therapy is impeded because several major driver mutations fuel its growth (predominantly BRAF and NRAS)." (PMID 34063141, 2021). "BRAF gene regulates the MAPK signaling cascade along with activating mutations in the serine in human melanoma cells." (PMID 33473265, 2021). "Cancer-associated fibroblasts (CAFs) were isolated from a biopsy of cutaneous melanoma metastases (patient diagnosed with MM with an NRAS mutation (Q61R) but a BRAF wild-type)." (PMID 34638245, 2021). "More interestingly, we found that low TYR expression displays a significant association with unfavorable prognosis in BRAF-mutated melanoma subtypes." (PMID 34199192, 2021). "In BRAF mutated melanoma patients, elevated glucose utilisation is also observed when uptake of the labeled glucose analogue fluorodeoxyglucose (FDG) is assessed using positron emission tomography (PET)." (PMID 34830962, 2021). "CCND1 amplifications have been found in 17% of BRAF-driven melanomas (11% in melanoma) and have been associated with poor prognosis and intrinsic resistance to BRAFi-based targeted therapy." (PMID 34066022, 2021). "G361, a human melanoma cell line harboring heterozygous BRAF V600E mutations, was used as a control." (PMID 34502061, 2021). "For example, BRAF inhibitors have been shown to be significantly effective in improving overall survival (OS) in patients with BRAF-mutated melanoma and have recently been approved for the treatment of BRAF-mutated non-small cell lung cancer (NSCLC)." (PMID 34947990, 2021). "The identified studies indicated that POLE and POLD1 mutations are biomarkers for immunotherapy across multiple cancer types, and BRAF mutation can improve antitumor activity of immunotherapy in melanoma." (PMID 34211853, 2021). "More than half of the newly diagnosed melanomas present the activating BRAF mutation BRAF V600E, which results in a dysregulated mitogen-activated protein kinase (MAPK) signaling activation." (PMID 33669949, 2021). "It is even observed that the model corrected the position of the two BRAF mutated cell lines, but whose sensitivity is experimentally low (melanoma cell line HT-144 and colorectal cell line HT-55)." (PMID 33507915, 2021). "The expression of various receptor tyrosine kinases, including AXL, PDGFRB, and EGFR, in cutaneous melanoma occurs in MITFlow melanoma cells with a proinvasive potential and has been associated with BRAF/MEK inhibitor resistance." (PMID 33916908, 2021). "Approximately 60% of melanomas harbor an activating BRAF (v-raf murine sarcoma viral oncogene homolog B1) mutation V600E (changing valine to glutamic acid and being highly predominant over other infrequent BRAF mutations)." (PMID 34063141, 2021). "Consistently, STING activation upregulates PD-L1 on tumor cells and has a beneficial impact on the anti-tumor immune response in B16F10 and BRAF-mutated murine melanoma animal models." (PMID 34830754, 2021). "Major strides have been made in the treatment of advanced melanoma with BRAF mutation in recent years." (PMID 34504796, 2021). "The availability of targeted therapies with different tolerability profiles provides additional options for the management of BRAF-mutated melanoma." (PMID 34590600, 2021). "The AC heard from clinical experts that the treatment of patients with unresectable or metastatic BRAF V600 mutation-positive melanoma is evolving, with new immunotherapy and other treatments becoming available." (PMID 32291725, 2021). "In conclusion, FASN plays a role in BRAF-mutated melanoma progression, thereby creating novel therapeutic opportunities for the treatment of melanoma." (PMID 34068792, 2021). "A375 and SK-MEL-28 are two human melanoma cell lines with the BRAF mutation at V600E; they were selected as representative models according to the Melanoma Aggressiveness Score (MAGS)." (PMID 34066184, 2021).
melanoma (continued). "Several BRAF inhibitors (BRAFi) have been developed to specifically inhibit BRAFV600 mutations that improve melanoma survival, but resistance and secondary cancer often occur." (PMID 34066966, 2021). "OV is a promising treatment option, as it can be used to treat both BRAF and non-BRAF-mutated melanomas." (PMID 34679325, 2021). "This treatment is particularly suitable as first-line therapy for patients with symptomatic BRAF mutated melanoma with rapid progression and high therapeutic pressure." (PMID 33993415, 2021). "In the present study, higher efficacy was seen in patients with BRAF wild-type melanoma than in those with BRAF-mutated melanoma." (PMID 34115870, 2021). "For example, the BRAF V600 mutation in melanoma can result in the suppression of melanoma antigen and the reemergence of an immunosuppressive tumor microenvironment through constitutive activation of the MAPK pathway." (PMID 33531976, 2021). "Melanoma cells with KRAS or BRAF mutations have increased glucose uptake as well as higher glycolysis, but they are also able to survive in low glucose conditions in comparison with normal cells." (PMID 33730175, 2021). "Many researchers have shown high MEK1 expression in BRAF-mutated melanoma due to the activation of RAF–MEK–ERK pathway." (PMID 34526571, 2021). "Previous data have indicated that the Spitzoid histomorphology per se is an unreliable predictor of Spitz lineage, also encompassing BRAF or NRAS-mutated melanoma." (PMID 34449585, 2021). "Several melanoma driver genes, including mutated BRAF, have been shown to control cellular metabolism." (PMID 34068792, 2021). "Search parameters included articles published up to 2021 with keyword search terms melanoma and thyroid cancer, BRAF mutation, and nucleocytoplasmic transport in cancer." (PMID 33578751, 2021). "Rare V600 BRAF mutations, such as V600R, V600D and V600M, have been associated with good response to BRAF inhibitors and acceptable OS compared to V600E/K-mutant melanoma patients." (PMID 33801689, 2021). "BRAF is considered one of the most common and well-known mutated kinases in human cancer, with driver mutations in several cancers, including melanoma, colorectal cancer, thyroid cancer and non-small cell lung cancer." (PMID 34116682, 2021). "To gain insights into the role of RICTOR in melanoma development, we overexpressed RICTOR in three BRAF-mutated melanoma cell lines (Colo829, A375, and SkMel5)." (PMID 34680615, 2021). "The combination of BRAF plus MEK inhibitors provides inspiring treatment options as a targeted therapy for patients with BRAF-mutated melanoma, with an improved overall response." (PMID 34885166, 2021). "Our laboratory identified the PMCA4b variant as a putative metastasis suppressor using BRAF mutant melanoma cell models." (PMID 33802790, 2021). "BRAF alterations, especially V600E, have been studied intensively as potential diagnostic biomarkers for different types of cancers, including melanoma, colorectal cancer, papillary thyroid carcinoma and hairy cell leukaemia." (PMID 33557011, 2021). "Nonetheless, it still remains to be examined how Nox4 derived ROS in BRAF mutated melanoma cells regulate their metastatic progression and drug sensitivity." (PMID 33451139, 2021). "Approximately 50% of melanomas harbor a mutation in the BRAF gene, with p.V600E being the most common variant." (PMID 33915880, 2021). "We confirmed MEK1 KinCon activity dynamics upon drug engagement using the patient-derived melanoma cell line A2058, which harbors the V600E hotspot BRAF mutation." (PMID 33808483, 2021). "Mutated BRAF genes are associated with the upregulation of proliferation, differentiation, survival, invasion, and angiogenesis of melanoma." (PMID 34360634, 2021). "Melanomas are most frequently characterized by BRAF and NRAS mutation and, more rarely, by c-KIT oncogene mutations, but tumor suppressor genes such as CDKN2A and PTEN have an important role in the development and prognosis of melanoma." (PMID 34209415, 2021).
melanoma (continued). "The effects of oleic acid, homovanillyl alcohol, and hydroxytyrosol on CM were assessed using viability assays performed 48 h post treatment of two BRAF mutated melanoma cell lines (A375 and MNT1)." (PMID 33430068, 2021). "For example, the somatic BRAF V600E mutation in melanoma can be induced by oxidative stress and loss of p16 results in elevated ROS and mitochondrial biogenesis of human melanocytes." (PMID 34777692, 2021). "Since both PI3K and BRAF are implicated in melanomas, we believe that targeting both PI3K and BRAF by a single selective inhibitor would be beneficial in reducing drug-induced toxicities." (PMID 37305163, 2021). "Clinical trials are currently investigating BRAF and MEK inhibitors in combination with ribociclib in BRAF-mutant melanoma and other solid tumors with BRAFV600 mutations." (PMID 34309585, 2021). "The HIF-1α-induced overexpression of antiapoptotic protein Mcl-1 (myeloid cell leukemia 1) was also observed in BRAF-mutated melanoma cells." (PMID 33918883, 2021). "Although the number of MITF-E318K carriers is low, the presence of BRAF mutation in sporadic melanomas of all of them (100% including the multiple lesions of patient EW29/Pt5) is intriguing and deserves confirmation in larger cohorts." (PMID 34573422, 2021). "The aim of our study was to assess the correlation between known prognostic factors of melanoma, mutational occurrence of BRAF and NRAS in the primary tumor, and sentinel lymph node status." (PMID 34209415, 2021). "BRAF-mutated tumors such as melanoma and colorectal cancer have been successfully treated by inhibition of BRAF and the downstream MAPK kinase (MEK)." (PMID 35127532, 2021). "We therefore deduce that profiling melanoma patients according to their BRAF mutational status is insufficient to assign effective therapy to the patient." (PMID 34112933, 2021). "An alternative to the use of vincristine is to utilize current melanoma treatment options as combination therapeutics, for example immunotherapeutics (such as anti-PD-1 targeting drugs) or compounds that target BRAF V600E mutations." (PMID 35008307, 2021). "The expression of several miRNAs in melanoma is altered by BRAFi and MEKi treatment and reprogramming of miRNA expression is involved in the emergence of drug resistance in BRAF mutated melanoma." (PMID 34063443, 2021). "Despite the efficacy of BRAF + MEK inhibitors in treating BRAF-mutated melanoma, about 20% of BRAF-mutated melanomas demonstrate resistance to this therapy." (PMID 37632820, 2021). "In 2002, a genome-wide screening discovered a point mutation of BRAF occurring more frequently in melanoma than other types of solid tumors." (PMID 34924562, 2021). "Mutations in the v-Raf murine sarcoma viral oncogene homolog B proto-oncogene (BRAF) are the most common coding region mutations that occur in 33–65% of cutaneous malignant melanomas." (PMID 34680938, 2021). "Mutations in the BRAF gene (V600E) are more common in melanoma that develops in parts of the body that are exposed to solar radiation." (PMID 34203771, 2021). "It is an inhibitor of the kinase activity of the BRAF kinase that has the valine to aspartate mutation at position 600 (i.e., the BRAF(V600E) kinase), which is present in at least 60% of all melanomas." (PMID 34206728, 2021). "SPRED1 deficiency enhanced melanoma cell proliferation under mutant BRAF inhibition via the reactivation of MAPK activity." (PMID 34804979, 2021). "Previous research has indicated that the use of BRAF kinase inhibitors (vemurafenib and dabrafenib) to treat melanoma patients bearing the BRAF-activating mutation V600E results in tumor regression, followed by quick development of drug resistance." (PMID 34685720, 2021).
melanoma (continued). "For detecting BRAF mutations in melanoma patients, the real-time PCR (RT-PCR) approach utilizes a set of primers: one for targeting BRAF mutations and another for identifying the wild-type sequence." (PMID 33801689, 2021). "Approximately 40% of melanomas harbor the V600 BRAF mutation, leading to constitutive activation of the MAPK signaling pathway." (PMID 33435389, 2021). "NECTIN4 was highly expressed in BRAF-mutated melanoma and its high expression was associated with disease-free survival." (PMID 33478111, 2021). "The proportion of patients with BRAF-mutated melanoma is reportedly higher in the USA than in Japan." (PMID 34115870, 2021). "Overall, the treatment outcomes and the observed safety profile with combination treatment with cobimetinib plus vemurafenib, were consistent with the pivotal phase 3 data in a population of patients with advanced melanoma and BRAF mutations." (PMID 34298804, 2021). "Vemurafenib, a BRAF inhibitor, has been shown to improve outcomes in the majority of melanoma patients harboring the highly prevalent BRAF V600E mutation." (PMID 33849069, 2021). "Following the development of therapies to target BRAF, the most frequently found mutation in melanoma, promising therapeutic responses were observed." (PMID 34066022, 2021). "The occurrence of MAP2K1/2 mutations was identified as a mechanism related to BRAF inhibitor resistance in melanoma." (PMID 35069558, 2021). "This positional paper provides an overview of the pathophysiology and clinical presentation of BRAF-mutated melanoma and presents current guidelines and recommendations for BRAF mutation testing." (PMID 34068774, 2021). "This led to the discovery of pembrolizumab (Keytruda), an anti-PD-1 antibody intended for metastatic or unresectable melanoma previously treated with ipilimumab, or BRAF V600 mutated patients previously treated with a BRAF inhibitor." (PMID 34200997, 2021). "Here we identified miR-129-5p as a novel tumor suppressor in BRAF mutated melanoma, which expression is increased during response to BRAF inhibition, but repressed in an EZH2 dependent manner during activated BRAF signaling." (PMID 34063443, 2021). "The main melanoma mutation is the substitution of a valine to glutamine in codon 600 (V600E) of the serine-threonine kinase BRAF(V600E) which accounts for ~50% of cases." (PMID 33672955, 2021). "Other amino acid substitutions in the protein are possible, such as those observed in V600K mutations (representing ~20% of BRAF mutations in melanoma)." (PMID 34203771, 2021). "NRAS and NF1 mutations are less frequent than BRAF mutations, occurring in approximately 10-25% and 14% of melanomas, respectively." (PMID 34025662, 2021). "First, A375, a human melanoma cell line with a BRAF V600E mutation and wild type PTEN, was exposed to the NO donor, DETA NONOate for defined times up to 24 h." (PMID 33643925, 2021). "As expected, KRAS mutation dependence was observed in colon, pancreatic and lung cancer cell lines, NRAS mutation dependence in melanoma lines, and BRAF mutation dependence in colon, thyroid and melanoma lines." (PMID 34254730, 2021). "More than half of all melanomas have BRAF mutations, with the V600E mutation accounting for nearly all." (PMID 35003391, 2021). "Next, we analyzed C > T transitions in four mutational subtypes of melanoma, BRAF-, NRAS-, NF1-mutant samples and triple-wildtype samples." (PMID 33578810, 2021). "ECCA had a selectively strong inhibitory activity against the growth of BRAF-mutated and BRAF-wild-type melanoma cells but had little effect on normal human primary melanocytes." (PMID 34103468, 2021). "The proportion of patients with melanoma harbouring BRAF mutation reportedly ranges from 50 to 60% in the USA, but is only about 30% in Japan." (PMID 34115870, 2021).
melanoma (continued). "Signalling requiring the PI3K pathway and the activation of the PI3K pathway itself have both also been implicated in the development of melanoma’s resistance to BRAF/MEK inhibitors and immune checkpoint inhibitors." (PMID 33549048, 2021). "For melanoma, mutations in the key signal components, including BRAF, NRAS, NF1, and KIT, are responsible for the hyper-activation of the MAPK pathway." (PMID 34924562, 2021). "Despite its heterogeneous etiology and the highest mutation rate of any neoplastic disease, more than 50% of melanomas carry activating mutations in codon 600 of the serine–threonine protein kinase BRAF." (PMID 33810045, 2021). "Vemurafenib or dabrafenib are not approved for this indication yet, and are used off label also in the USA, but are marketed for BRAF-mutated melanoma worldwide and the efficacy of vemurafenib plus rituximab seems higher than that of Moxe." (PMID 34202156, 2021). "The signature predicted trametinib sensitivity in all BRAF-mutated melanomas, as expected, and in 11/15 CUPs (73%), while it predicted sensitivity only in 3/10 early metastatic tumors of known origin." (PMID 33941777, 2021). "Inhibition of EZH2 with the specific inhibitor EPZ-6438 (EPZ) significantly increased miR-129-5p expression in BRAF mutated melanoma cell lines (A375, WM35), even in BRAFi resistant cell lines (A375R, WM35R)." (PMID 34063443, 2021). "VEM, which is commonly used in targeted therapy for melanoma with the BRAF V600E-positive mutation, is a competitive inhibitor of the mutated BRAF protein." (PMID 34822435, 2021). "Our study was designed for a comprehensive evaluation of the relationship between CT imaging features and the BRAF mutation status in melanoma lung metastases." (PMID 33915880, 2021). "Strikingly, vemurafenib-resistant melanoma cells harboring BRAF V600E mutation display substantial increase in actin stress fiber formation, reduced apical actin pool and remarkably flattened cell shape in the presence of prolonged vemurafenib." (PMID 33467099, 2021). "BRAF mutations are involved in approximately half the cases of malignant cutaneous melanomas, as well as in sinonasal and other melanomas to a lesser extent, and represent a paradigm of successful molecular targeting therapies." (PMID 33435440, 2021). "Now an important added value should be the capability to choose the more promising first-line therapeutic approach, such us selecting targeted or ICB therapies in BRAF mutated melanomas." (PMID 34207514, 2021). "Oncogenic mutations in BRAF are present in up to 50% of melanomas, the most frequent being a valine to glutamic acid at position 600 (V600E), which constitutively activates the BRAF/MEK/ERK-signaling pathway, transmitting constant cell growth signals." (PMID 33467521, 2021). "Accordingly, histomorphological studies revealed that BRAF-mutated melanomas had a thicker epidermis and more pigmented cells with a greater tendency to form nests than wild-type melanomas." (PMID 33954019, 2021). "Shaffer and colleagues described a transient, transcriptionally encoded preresistance state in 2 BRAF mutant melanoma cell lines that cells can transition into and out of in the absence of drug." (PMID 34061819, 2021). "All four established MUG Mel3 melanoma cell lines, as well as the tumor tissues, exhibited high VAFs for the BRAF V600E allele." (PMID 34768746, 2021). "The RAC1 P29S mutation is more frequent in melanomas BRAF and NRAS wild-type and occurs early in tumorigenesis." (PMID 34123788, 2021). "It is estimated that more than 90% of patients with BRAF mutated melanoma develop resistance within 1 year of monotherapy." (PMID 34804975, 2021). "Low activity of demethylases results in accumulation of aberrations in the methylation of histones (e.g., H3K27me3), DNA, and RNA, further inducing drug resistance and heterogeneity of patient-derived BRAF-mutated melanoma cells." (PMID 33918883, 2021).